KIF20A (kinesin family member 20A)
Diseases named in the same sentence as KIF20A in open-access papers (continued):
Sharing a sentence is not in itself a finding about the gene and the disease.
cancer (continued). "As a consequence, the induction of abnormal spindle formation through FOXM1 and its downstream target KIF20A, may represent a novel strategy for overriding taxane resistance as well as for cancer treatment, as ensuing aberrant mitosis will culminate in senescence and/or cell death." (PMID 25961928, 2016). "Notably, KIF20A knockdown could trigger ferroptosis of cancer cells." (PMID 40914946, 2026). "Kinesin Family Member 20 A (KIF20A), A motor protein bound to microtubules that is crucial for cytokinesis and cell progression, is overexpressed in multiple malignancies and correlates with aggressive phenotypes, metastasis, and chemoresistance." (PMID 41267030, 2025). "CDC20, KIF20A and PTTG1 combined knockdown inhibited cell viability and DNA replication in both LGG (LN229/HS683) and GBM (U87MG/U343) cancer cell lines." (PMID 40047299, 2025). "Kinesin family member 20A (KIF20A) is an important member of the kinesin family, exhibiting high expression levels across various cancers." (PMID 40600015, 2025). "Due to their likely role in promoting cancer progression, ORC1L, KIF20A, DLGAP5, and RAB3B were selected as marker genes for downstream analysis." (PMID 37948380, 2023). "FOXM1 has an effect on the biological functions of various cancers through synergistic interactions or transcriptional regulation with CENPF and KIF20A." (PMID 35410446, 2022). "Further, graph centrality measures suggested the importance of upregulated genes such as BIRC5, UBE2C, BUB1B, KIF20A and PTH1R in cancer." (PMID 34728699, 2021). "Both KIF20A and KIF18B support mitosis and meiosis, as well as being potential biomarkers and molecular targets for cancer therapy." (PMID 34112092, 2021). "Upon merging the scaled matrix of KIF20A expression from both TCGA and GTEx databases, we observed that KIF20 was highly expressed in a variety of cancer types, including KIRC." (PMID 33232285, 2020). "KIF20A and RGS1 genes have been reported to play critical roles in the development and progression of cancer, and promote the proliferation, migration and invasion of cancer cells." (PMID 32467670, 2020). "Meanwhile, we also chose 5 random cancer-related genes for mRNA detection, and found that GADD45A, HBP1, and SESN2 were significantly up-regulated, whereas KIF20A and TOP2A were down-regulated, compared to the 0 h group (*P < 0.05)." (PMID 32850392, 2020). "KIF2C and KIF20A were reported, in a study based on ChIP-chip assays, as the target of E2F family including E2F1, E2F4, and E2F6 in normal and cancer cells of breast tissue." (PMID 30813560, 2019). "KIF20A expression in CRC and paracancerous tissues was analyzed by immunohistochemistry, and we found that strong staining was observed in the cancer specimens." (PMID 31841120, 2019). "We identified 25 recently published articles and found that patients with cancer and high KIF2 and KIF20A expression tended to have shorter OS than those with low expression." (PMID 31725680, 2019). "Increasing studies showed that kinesin family member 20A (KIF20A) was overexpessed in several types of cancer, and its overexpression correlated with the oncogenesis and prognosis of cancers." (PMID 30105795, 2018). "In conclusion, our data showed that KIF20A is a novel TAA and a potential target for anticancer immunotherapy for cancer cells expressing KIF20A at least in an HLA-A2-restricted situation." (PMID 21179034, 2011). "KIF20A, a motor protein belonging to the dynein family, exhibits a negative correlation with clinical outcomes in cancer." (PMID 40136455, 2025). "Future research could explore the correlation between three kinesin genes (KIF4A, KIF20A, and KIF11) and cancer stem cells, potentially leading to new discovery.However, there were a few limitations in this study." (PMID 41462522, 2025). "Ideal targets are kinesins whose expression is largely restricted to cancer cells and/or whose function is dispensable in non-malignant cells, as has been described for KIF20A, KIFC1, and KIF18A." (PMID 40002279, 2025).
cancer (continued). "Further research is essential to evaluate the selective targeting of KIF20A in cancer treatment while minimizing adverse effects on normal tissues." (PMID 39272816, 2024). "KIF20A plays a crucial role in normal cellular division and transport processes, so targeting this kinesin in cancer cells without affecting its function in healthy cells is critical to avoid unwanted side effects." (PMID 39272816, 2024). "Multivariate Cox-proportional hazard model analysis was first conducted using hsa-mir-1247-3p, KIF20A, RAB3B, ORC1L, and DLGAP5 expression, MDSC, Th2, and HSC infiltration, LUAD cancer patient age and cancer stage as covariates to identify key markers promoting loss of patient survival rate." (PMID 37948380, 2023). "The KIF20A gene was highly expressed in the RCC and BC samples, while it was expressed at low levels in normal tissue samples, indicating its potential regulatory role in these cancers." (PMID 37310408, 2023). "Then, these three peptides were used to stimulate CD8+T cells isolated from PBMC of HLA-A2 positive healthy donors, as a results, KIF20A peptides induced CTL with specific cytotoxicity, peptides were naturally processed and expressed on the surface of cancer cells." (PMID 36798768, 2023). "Two well-known KIF members, KIF2A and KIF20A, were investigated to evaluate their potential values as novel prognostic biomarkers in human cancer." (PMID 31725680, 2019). "Numerous studies have shown Kinesin family member 20A (KIF20A) may play a critical role in the development and progression of cancer." (PMID 28081138, 2017). "These demonstrations imply that KIF20A expression may help us to identify patients with PLNM, and that these patients should undergo more aggressive therapy in order to reduce cancer mortality." (PMID 27941992, 2016). "Among these candidates, KIF20A captured our attention because it is a member of the KIF family, which has been shown to play an important role in the cell division and proliferation of cancer cells." (PMID 27036048, 2016). "In this study, we identified KIF11, KIF20A, KIF21, KIF25, MYO1G, MYH1 and TPM2 as proteins whose depletion causes growth inhibition and non-apoptotic cell death in cancer cells." (PMID 23071517, 2012). "We selected six DplUSE-containing genes (KIF20A, EXT2, CLDN12, MBNL2, MED18, DKC1) from the 31 orthologous genes identified by the bioinformatic script that are common to human, mouse, and zebrafish and that have a relevant physiological function in malignant neoplasms." (PMID 41505098, 2026). "Moreover, the inhibitory effects of KIF20A against cancer cell proliferation were not validated in vivo." (PMID 36619388, 2022). "Actions of KIF20A in the chemo-sensitivity of cancer cells have not been reported." (PMID 34491228, 2021). "The FOXM1 transcription factor is a proto-oncogene involved in cell cycle progression, cell proliferation, tumorigenesis and cancer progression, and many of its target genes (> 20) were downregulated in paclitaxel-residual MDA-MB-231 cells including AURKB, CCNB1, PLK1, PLK2, and the kinesin KIF20A." (PMID 28187446, 2017). "Furthermore, despite the fact that ATF4 itself was not deregulated by Ocoxin in all the analyzed cancer models, it arises as a central protein in the correlation among the genes altered by the compound (except for KIF20A, RAD54L and ESPL1) in common in COAD, PAAD, PRAD and TNBC." (PMID 40176904, 2025). "Moreover, studies have shown that KIF20A interacts with other proteins involved in cell cycle regulation and cancer development, such as Aurora-A and PLK1, suggesting that KIF20A may play a crucial role in the regulation of cell division and cancer progression." (PMID 37310408, 2023).
infection (3 papers, 2021 to 2025). The state of being infected such as from the introduction of a foreign agent such as serum, vaccine, antigenic substance or organism. "In MDA-MB-231 cells, the estimated stem cell frequency was 1 in 315 with control sgRNA, which decreased to 1 in 845 and 1 in 1,780 upon infection with KIF20A sgRNA #1 and sgRNA #3, respectively." (PMID 41392981, 2025).
KIF20A also shares sentences with these, for which no sentence is quoted: non-small cell lung carcinoma (6 papers); Cirrhosis (2); congenital cardiomyopathy (2); gastric tumor (2); myocarditis (2); neuroblastoma (2); adenocarcinoma (1); basal cell carcinoma (1); benign tumors (1); biliary tract cancer (1); brain cancer (1); brain glioma (1); breast tumors (1); cardiovascular diseases (1); Cm (1); colorectal tumor (1); endometriosis (1); familial restriction Familial Isolated Restrictive Cardiomyopathy (1); familial restrictive cardiomyopathy-6 (1); heart defects (1); HIV-1 infection (1); large cell lung cancer (1); liver cirrhosis (1); malaria (1); malignant glioma (1); Meckel-Gruber syndrome (1); oral squamous cell carcinoma (1); pancreatic adenocarcinoma (1); rectal adenocarcinoma (1); rheumatoid arthritis (1).
A further 4 diseases each share a sentence with KIF20A in 1 paper.